CD4 (CD4 molecule)
Diseases named in the same sentence as CD4 in open-access papers (continued):
Sharing a sentence is not in itself a finding about the gene and the disease.
blood disease (1 paper, 2017). A disease that occurs in the blood. "The predicted dominant CD4 T cells in T-ALL and dominant B cells in B leukemia were consistent with existing knowledge regarding these two typical blood diseases." (PMID 28084418, 2017).
bone fracture (1 paper, 2019). "A prospective multicenter study (>600 patients) is currently ongoing to confirm the promising potential of the CD8+ TEMRA/CD4+ TReg ratio as a potential biomarker for predicting the healing outcome in human bone fracture patients." (PMID 31475013, 2019).
bone-resorptive diseases (1 paper, 2025). "Understanding the mechanisms that drive CD4+ T lymphocyte senescence and their contribution to chronic inflammation and bone-resorptive diseases unveils new therapeutic opportunities." (PMID 40665343, 2025).
borna disease (1 paper, 2022). An encephalomyelitis of horses, sheep and cattle caused by borna disease virus. "In animals, lesions in the CNS during natural Borna disease or experimental infection are caused by a T cell-mediated immunopathology; symptoms begin with the appearance of CD4 and CD8 T cells in the brain." (PMID 35788177, 2022).
Bovine mastitis (1 paper, 2025). INFLAMMATION of the UDDER in cows. "Surprisingly, our previous research found that although the proportion of CD4+CD8+ T cells in dairy cows is minimal, these cells exhibit diversity and pleiotropic activity, playing a crucial role in the immune response to bovine mastitis." (PMID 41142813, 2025).
Bowens disease (1 paper, 2015). "Patients with arsenic-induced Bowens disease have significantly reduced circulating CD4+ T cells compared to control patients and show intralesional CD4+ apoptosis." (PMID 25658450, 2015).
brain inflammation (1 paper, 2015). "The observed decrease in CD4% may have lessened cross reactive antibody production in the younger children, leading to a brief period of decreased brain inflammation." (PMID 25887094, 2015).
bronchopulmonary dysplasia (1 paper, 2016). Bronchopulmonary dysplasia is a chronic respiratory disease that results from complications related to lung injury during the treatment of infant acute respiratory distress syndrome in low-birth-weight premature infants or from abnormal lung development in older infants. "We found no influence of CD4+ T-cell activity on short-term outcomes (IVH: intraventricular hemorrhage; PVL: periventricular leukomalacia; ROP: retinopathy of prematurity; BPD: Bronchopulmonary Dysplasia; death), at birth or at 30 days of life." (PMID 28070527, 2016).
C. perfringens Infection (1 paper, 2023). "L. lactis treatment was essential to overcome the depleting effects caused by C. perfringens infection on CD4+ αβ T cells populations." (PMID 38164397, 2023). "C. perfringens Infection was associated with spatial and temporal decreases in mononuclear phagocytes and CD4+ αβ T cells." (PMID 38164397, 2023). "However, the combination of rL. lactis treatment and subsequent C. perfringens infection resulted in the increase of both CD3ζ + CD4+ and CD3ζ + CD8α + αβ T across the intestine when compared to the infected or control chickens, respectively." (PMID 38164397, 2023). "However, C. perfringens infection resulted in a significant reduction in intestinal CD4+ αβ T cell while an increase in CD8α + αβ T cell was observed thereby shifting this ratio to 5:1, proportionally more in favor of CD8α + αβ T cells." (PMID 38164397, 2023).
campylobacteriosis (1 paper, 2021). Infections with bacteria of the genus campylobacter. "Thus, in order to understand the impact of HIV in campylobacteriosis, future studies should include HIV serological status data, including CD4 cell count and/or viral load and if possible the intake or not of highly active antiretroviral treatment (HAART)." (PMID 33503068, 2021).
capillary leak syndrome (1 paper, 2024). A syndrome characterized by leakage of intravascular fluids into the extravascular space. "This study resulted in increased numbers of active circulating CD4 and CD8 T cells, and identified specific changes in serum cytokines and peripheral CD4 T cell subsets associated with capillary leak syndrome, the major toxicity of immunotoxin therapies." (PMID 38384463, 2024).
cardiac sarcoidosis (1 paper, 2022). Sarcoidosis affecting the tissues of the heart. "Moreover, some reports indicate that immunohistochemistry may be helpful for diagnosis; although both are caused by T cell-mediated autoimmune inflammation, CD4+ helper T cells are dominantly recruited in cardiac sarcoidosis whereas CD8+ cytotoxic T cells more often occur in giant cell myocarditis." (PMID 35011991, 2022).
cardiotoxicity (1 paper, 2025). Toxicity that impairs or damages the heart. "Those with cardiotoxicity had a noticeable increase in circulating CD4 + FOXP3 + and CD8 + PRF1 + T cells at disease onset." (PMID 41510228, 2025).
cartilage-hair hypoplasia (1 paper, 2025). Cartilage-hair hypoplasia is a disease affecting the bone metaphyses causing small stature from birth. "In cartilage-hair hypoplasia (CHH; n = 6, 13%), DNTs (50%), naïve CD8+ (50%), and γδ T cells (100%) were above, while RTEs (83%) and naïve CD4 + T cells (100%) below the reference range." (PMID 41249610, 2025).
cataract (1 paper, 2018). Partial or complete opacity of the crystalline lens of one or both eyes that decreases visual acuity and eventually results in blindness. "Our group recently reported higher CD4+ T-cell reactivation and reduced regulatory T-cell populations in peripheral blood of HIV-positive adults with cataracts, relative to HIV-negative adults with cataracts." (PMID 29351788, 2018).
cauda equina syndrome (1 paper, 2024). Cauda equina syndrome refers to a group of symptoms that occur when some of the nerves in the cauda equina (the bundle of nerves that spread out from the bottom of the spinal cord) become compressed and/or damaged. "In patients with meager CD4 cell count (< 50 cells), CMV can present as an acute lumbosacral radiculitis with an acute proximal asymmetrical weakness and could evolve to cauda equina syndrome." (PMID 39021464, 2024).
cavernous cerebral malformation (1 paper, 2017). "SPG21 is a negative pro-inflammatory CD4+ cells regulator that can lead to spastic paraplegia while the aberrant PDCD10 expression can be associated with the development of cavernous cerebral malformation." (PMID 28423529, 2017).
cellulitis (1 paper, 2007). Inflammation of the dermis and subcutaneous tissues caused by a bacterial infection. "This patient was an intravenous drug user who was admitted to hospital with a diagnosis of cellulitis of the inferior limb; he had a median CD4 cell count lower than 200/μl, and a median log10 HIV plasma viral load > 2.99 cp/ml." (PMID 17470274, 2007).
Central diabetes insipidus (1 paper, 2022). A form of diabetes insipidus related to a failure of vasopressin (AVP) release from the hypothalamus. "Using scRNA-seq in the sample acquired at time of central diabetes insipidus diagnosis for PD-AML 3, we detected the majority of expanded clonotypes including both CD8+ and CD4+ T cells." (PMID 35017151, 2022).
cervical dystonia (1 paper, 2024). "The same study also showed an increased population of B cells, monocytes, and an increased ratio of CD8+ cytotoxic cells compared to CD4+ helper cells with an increase in proinflammatory cytokines like IL-5, IL-2, PIGF, VEGF-D, IL-1ß in patients of cervical dystonia." (PMID 39651491, 2024).
chondrosarcoma (1 paper, 2021). A malignant cartilaginous matrix-producing mesenchymal neoplasm arising from the bone and soft tissue. "CD4+ T cells were present in 21% of the 61 chondrosarcoma tumors analyzed and CD8+ T cells were present in 44% of the 62 chondrosarcoma tumors analyzed (conventional and dedifferentiated combined)." (PMID 33912442, 2021). "There was no statistical difference in CD4+ TILs between conventional and dedifferentiated chondrosarcoma (p=0.90)." (PMID 33912442, 2021). "The number of CD4+ T cells detected ranged between 0.0 and 7.9 lymphocytes per high-power field (mean n=0.16 ± 1.0, n=61), whereas that of CD8+ T cells ranged between 0.0 and 52 lymphocytes per high-power field (mean n=5.0 ± 11, n=62) in chondrosarcoma (conventional and dedifferentiated combined)." (PMID 33912442, 2021).
chromophobe renal cell carcinoma (1 paper, 2023). Chromophobe renal cell carcinoma is a rare subtype of renal cell carcinoma, originating from the intercalating cells of the collecting ducts and macroscopically manifesting as a well-circumscribed, highly lobulated, solid tumor that is usually diagnosed at an early stage. "Chromophobe renal cell carcinoma (KICH) presented similar distributions in its scores for CD4+ cells (p = 0.17), macrophages (p = 0.4904), Th2 cells (p = 0.151), and Tgammadelta cells (p = 0.5525)." (PMID 36612301, 2023).
chronic otitis media (1 paper, 2006). Chronic form of otitis media (disease). "Thus, based on the data presented here, we conclude that the HAART therapy in HIV-infected children below 6 years of age was associated to a lower prevalence of chronic otitis media, probably due to an increase in their CD4+ T lymphocyte counts." (PMID 17143430, 2006). "Prevalence of chronic otitis media, as well as CD4+ lymphocyte count were compared between groups in use of HAART and the group without HAART." (PMID 17143430, 2006). "The use of HAART was associated to reduction in prevalence of chronic otitis media in HIV infected children, probably due to increase in mean CD4+ lymphocyte count." (PMID 17143430, 2006).
chronic venous insufficiency (1 paper, 2022). Chronic form of venous insufficiency (disease). "The main expression markers of the CD4 + Th17+ switch were strongly activated in chronic venous insufficiency and in advanced ulceration." (PMID 35883458, 2022).
Chylothorax (1 paper, 2025). The presence of chyle in the thoracic cavity. "Neonates with acquired chylothorax seemed to have higher absolute numbers of lymphocytes and T-cell subsets (CD3+, CD3+CD4+, CD3+CD8+) compared to those with congenital chylothorax, although not significantly." (PMID 41256863, 2025).
clear cell carcinomas (1 paper, 2020). "A subgroup of clear cell carcinomas with microsatellite instability where found to have increased CD8+ TILs, a higher CD8+/CD4+ ratio, and higher PD-1+ TILs." (PMID 32937961, 2020).
CNS demyelination (1 paper, 2011). A loss of myelin from nerve fibers in the central nervous system. "T cell depletion, T cell knockout and T cell adoptive transfer experiments suggest that both CD8+ and CD4+ T cells contribute to HSV-IL-2-induced CNS demyelination with CD8+ T cells being the primary inducers." (PMID 21364747, 2011).
cognitive function (1 paper, 2020). "On the one side, these results can be interpreted as meaning that CD8+ Temrahi and CD8βhi T cells, together with high IFNγ-producing CD4+ T cells and the presence of HLA-B8, are immunological biomarkers associated with unhealthy aging (ie, impaired brain cognitive function)." (PMID 33324408, 2020).
colon adenoma (1 paper, 2020). An adenoma that arises from the colon. "This suggests that either CD4+ T cells alone or CD4+ T cells in concert with CD8+ T cells mediate suppression of mouse colon adenoma formation." (PMID 31793740, 2020). "To test whether tumor‐infiltrating T cells affect colon adenoma formation in Apcfl/fl‐Cdx2CreERT2 mice, we continuously injected them with anti‐CD4 and anti‐CD8 neutralizing antibodies during and after tumor initiation." (PMID 31793740, 2020).
conjunctival cancer (1 paper, 2025). A malignant neoplasm involving the conjunctiva. "We also identified HIV-1 viremia as a risk factor for conjunctival cancer, both before and after adjustment for CD4 count." (PMID 39736138, 2025).
conjunctival squamous cell carcinoma (1 paper, 2013). A low-grade squamous cell carcinoma that arises from the conjunctiva. "Conjunctival microvasculopathy and conjunctival squamous cell carcinoma were common in patients with a CD4+ T cell count of <200 cells/μl." (PMID 23710936, 2013).
contagious pleuropneumonia (1 paper, 2020). A pleuropneumonia of cattle and goats caused by species of mycoplasma. "There are several reports documenting an increased population of IL-17A producing T cells and secretion of IL-17A in pigs, such as the presence of Actinobacillus pleuropneumoniae specific Th17 cells [CD4+CD8αdimIL-17A+] in the blood and lungs of porcine contagious pleuropneumonia infected pigs." (PMID 33391267, 2020).
cor pulmonale (1 paper, 2023). Hypertrophy and dilation of the right ventricle of the heart that is caused by pulmonary hypertension. "These variables were used in the binary logistic regression analysis, which showed that CD4 counts of <392 cells/μL (aOR27.432, CI 2.018, 372.960), cor pulmonale (aOR16.702, CI 1.864, 149.673), and age (aOR1.111, CI 1.007, 1.227) were independent risk factors for 6-month re-admission." (PMID 36769584, 2023).
cortical atrophy (1 paper, 2019). "By correlating the rates of cortical atrophy and absolute counts of CD4+ and CD8+ cells similar significant clusters could be obtained." (PMID 31417557, 2019).
cutaneous papillomas (1 paper, 2014). "In cutaneous papillomas caused by CRPV, a mostly CD8+ T cell infiltration of the epithelium, with very few accompanying CD4+ T cells, was demonstrated." (PMID 25121947, 2014).
dendritic cell neoplasms (1 paper, 2024). "The 5th edition of the WHO Classification of Hematolymphoid Tumors subcategorizes the dendritic cell neoplasms under the spectrum of histiocytic/dendritic cell neoplasms based on their histogenesis and their distinct immunophenotypic profile (positive for CD45, CD4, CD68, CD163, and lysozyme)." (PMID 39592527, 2024).
dependent (1 paper, 2018). "We have previously shown that OT-II cells can trigger antigen-dependent neutrophil recruitment within 4 h in a planted antigen model of CD4+ T-cell-dependent glomerulonephritis." (PMID 29467472, 2018).
dermatomycoses (1 paper, 2022). "Antifungal treatment was administered when patients presented with dermatomycoses or oral thrush, or in some cases in the absence of clinical symptoms when CD4+ T-cell numbers were <200 cells/μl." (PMID 35250957, 2022).
diabetic neuropathy (1 paper, 2017). A chronic, pathological complication associated with diabetes mellitus, where nerve damages are incurred due to diabetic microvascular injury involving small blood vessels that supply these nerves, resulting in peripheral and/or autonomic nerve dysfunction. "In respect to specific diabetic complications, the number of Tregs defined by the CD127 marker (CD4+CD25highCD127low) showed a significant positive correlation with the presence of diabetic neuropathy (p = 0.037)." (PMID 28553653, 2017). "In contrast to diabetic neuropathy, Treg numbers as defined by CD127 (CD4+CD25highCD127low) and/or FoxP3 markers (CD4+CD25highFoxP3+ or CD4+CD25highCD127lowFoxP3+) were inversely correlated with HDL cholesterol and ApoAI." (PMID 28553653, 2017).
distal myopathy (1 paper, 2018). Distal myopathy refers to a group of muscle diseases which share the clinical pattern of predominant weakness and atrophy beginning in the feet and/or hands. "Similar to equine IMM, increased skeletal muscle MHC class I expression and perivascular and endomysial lymphocytic infiltrates (CD3+, CD4+, and CD8+) were found in this family with Laing distal myopathy, along with rimmed vacuoles, which are not a feature of equine IMM." (PMID 29510741, 2018).
drug allergy (1 paper, 2015). Immunologically mediated adverse reactions to medicinal substances used legally or illegally. "Numerous factors have been associated with NVP toxicity, including high current and nadir CD4 counts, undetectable viral load, female sex, abnormally elevated baseline transaminases, history of drug allergy, lower body weight and high drug plasma levels." (PMID 26629333, 2015).
ductal carcinomas (1 paper, 2012). "Loss of PR expression was associated with decreased numbers of CD4+ T cells in ductal carcinomas (p = 0.008)." (PMID 22471961, 2012). "In ductal carcinomas, a significant (p < 0.001) association between higher total and intratumoral numbers of CD4+ and FOXP3+ lymphocytes and histological grade could be observed." (PMID 22471961, 2012). "In ductal carcinoma, a FOXP3+/CD4+ > 1 was significantly associated with better survival (p = 0.0005)." (PMID 22471961, 2012). "Remarkably however, a ratio > 1 of total FOXP3+/CD4+ TILs in ductal carcinoma appears to represent an independent favorable prognostic factor." (PMID 22471961, 2012). "High grade (G3) and estrogen receptor (ER) negative ductal carcinomas displayed significantly (p < 0.001) higher CD4+ and FOXP3+ lymphocyte infiltration while her2/neu over-expression in ductal carcinomas was significantly (p < 0.001) associated with higher FOXP3+ TIL counts." (PMID 22471961, 2012). "Significantly (p < 0.001) higher numbers of total and intratumoral CD4+ and FOXP3+ TILs were detected in ER negative as compared to positive ductal carcinomas." (PMID 22471961, 2012).
Dysmenorrhea (1 paper, 2022). Pain during menstruation that interferes with daily activities. "Patients with severe dysmenorrhea also had a decreased number of CD4+ CCR7+ cells (p = 0.022)." (PMID 35576870, 2022).
dysphasia (1 paper, 2020). "memory deficits, disorders of consciousness, dysphasia, and CD4+ T-cell counts between survivors and non-survivors (p < 0.05)." (PMID 33276733, 2020).
egg allergy (1 paper, 2020). A food allergy that is an allergy or hypersensitivity to dietary substances from the yolk or whites of eggs, causing an overreaction of the immune system which may lead to severe physical symptoms. "This study demonstrated that 1 year-old infants with challenge-confirmed IgE mediated egg allergy have increased frequency of circulating monocytes, reduced numbers of regulatory CD4 T cells and increased individual monocyte: CD4 T cell ratios relative to healthy controls." (PMID 33072108, 2020).
empyema (1 paper, 2021). An accumulation of pus in a body cavity, usually the pleural space. "The diagnostic accuracy of CD4+IL-9+, CD4+IL-17+, CD4+IL-22+, CD4+CD25+FOXP3+ T cells, and ADA in the differentiation of tuberculous from non-tuberculous effusions (malignant, empyema, and parapneumonic effusions)." (PMID 34925358, 2021).
encephalitozoonosis (1 paper, 2017). Infection with fungi of the genus encephalitozoon. "In conclusion, the present results showed that STZ-induced DM mice were more susceptible to encephalitozoonosis, probably due to a decrease in B-1, B-2 and CD4+ T cells and decreased IFN-γ levels, consistent with immunosuppressive condition." (PMID 29091912, 2017).
Endarteritis (1 paper, 2014). Inflammation of the arterial intima. "Pathological examination revealed infiltration of mononuclear cells, CD3+ T-cells, mainly CD8+ T-cells, CD4+ T-cells, and macrophages, in the renal interstitium with peritubular capillaritis, tubulitis, acute glomerulitis, and endarteritis." (PMID 25541735, 2014).
endometrial adenocarcinoma (1 paper, 2023). "Critical immune cells, including M1 macrophages, memory-activated CD4+ T cells, CD8+ T cells, and follicular helper T cells, have been proven beneficial to the survival of endometrial adenocarcinoma patients, and the exact underlying mechanism needs to be further studied." (PMID 36750966, 2023).
endometrial endometrioid adenocarcinoma (1 paper, 2024). A primary endometrial adenocarcinoma composed of neoplastic cells that form complex glandular patterns associated with budding and branching of the neoplastic glands. "Furthermore, a Korean study examined the presence of CD4+ and CD8+ T lymphocytes within endometrial endometrioid adenocarcinoma tissues." (PMID 38792013, 2024).